HNRNPM (heterogeneous nuclear ribonucleoprotein M)
Description:
Pre-mRNA binding protein in vivo, binds avidly to poly(G) and poly(U) RNA homopolymers in vitro. Involved in splicing. Acts as a receptor for carcinoembryonic antigen in Kupffer cells, may initiate a series of signaling events leading to tyrosine phosphorylation of proteins and induction of IL-1 alpha, IL-6, IL-10 and tumor necrosis factor alpha cytokines.
Synonyms: hnRNP M; HNRPM; NAGR1; HTGR1; HNRNPM4; HNRPM4; CEAR
Tractability: PROTAC: UniProt records ubiquitination sites on it; ubiquitination databases record sites on it; its protein half-life has been measured.
Gene: Protein-coding gene on chromosome 19 (8,444,767 to 8,489,114, forward strand). Ensembl gene ENSG00000099783.
Subcellular location: Nucleus, nucleolus
Subcellular location (Human Protein Atlas): Nucleoplasm
Pathways (Reactome):
Metabolism of RNA: Processing of Capped Intron-Containing Pre-mRNA; mRNA Polyadenylation; mRNA Splicing - Major Pathway
Disease: Dengue Virus-Host Interactions
Signal Transduction: FGFR2 alternative splicing
Gene Ontology:
Molecular function: protein binding; protein domain specific binding; RNA binding; nucleic acid binding
Biological process: alternative mRNA splicing, via spliceosome; mRNA splicing, via spliceosome
Cellular component: catalytic step 2 spliceosome; extracellular exosome; membrane; nuclear matrix; nucleoplasm; paraspeckles; spliceosomal complex; nucleus; nucleolus
Genetic constraint (gnomAD): Loss-of-function variants: 8 observed, 36.11 expected, observed/expected ratio (o/e) 0.22, 90% interval 0.13 to 0.4. The upper end of that interval is the gene's LOEUF score, 0.4, which puts it in group 1 of 6, group 1 being the genes least tolerant of losing a copy. Missense variants: 641 observed, 785.57 expected, observed/expected ratio (o/e) 0.82, 90% interval 0.76 to 0.87. Synonymous variants: 327 observed, 276.08 expected, observed/expected ratio (o/e) 1.18, 90% interval 1.08 to 1.3.
Homologues: Orthologues: macaque HNRNPM (100% identical), chimpanzee HNRNPM (99% identical), dog HNRNPM (99% identical), guinea pig HNRNPM (98% identical), mouse Hnrnpm (98% identical), rat Hnrnpm (97% identical), pig HNRNPM (94% identical), tropical clawed frog hnrnpm (60% identical), zebrafish hnrnpm (55% identical), Drosophila melanogaster rump (26% identical), Caenorhabditis elegans sup-46 (22% identical). Paralogues in human: MYEF2 (44% identical).
Diseases named in the same sentence as HNRNPM in open-access papers:
HNRNPM is named in the same sentence as 54 diseases in open-access papers, as found by Europe PMC text mining. Sharing a sentence is not in itself a finding about the gene and the disease. The quoted sentences say what the papers report.
breast carcinoma (30 papers, 2011 to 2025). "hnRNPM is associated with aggressive breast cancer and correlates with increased CD44s in patient specimens." (PMID 38106992, 2023). "Summarizing the current studies, we can conclude that hnRNPM promotes the exclusion of variant exons from CD44 pre-mRNA in breast cancer." (PMID 38106992, 2023). "High hnRNPM is associated with higher levels of CD44s, shorter overall survival and higher rates of lymph node metastases in breast cancer patients." (PMID 31737791, 2019). "As reported, the hnRNPM protein is an essential splicing factor that functions as a vital component in multiple cases of cancer metastasis, such as breast cancer, gastric cancer, colon cancer, hepatocellular carcinoma and prostate cancer." (PMID 39068483, 2024). "For instance, switching CD44 expression from the variant isoform (CD44v) to the standard isoform (CD44s) induced by hnRNPM protein plays a critical role in accelerating EMT in breast cancer by activating Akt signaling." (PMID 38346537, 2024). "An overexpression of hnRNPM in MCF-7 human breast cancer cells resulted in a decreased expression in CD44 isoforms containing exon v6 and an increased expression in CD44 isoform 4 with a slight change in the total level of CD44 transcripts." (PMID 38106992, 2023). "Reduced dissemination potential of murine T4 breast cancer cells and human LM2 breast cancer cells (MDA-MB-231-derived lung metastatic cells) with hnRNPM knockdown was also shown after intravenous injection into murine tail vein." (PMID 38106992, 2023). "The HnRNP family members HnRNPA1, HnRNPA2, HnRNPI, HnRNPM and HnRNPK have been reported to be highly expressed in breast cancer." (PMID 36052258, 2022). "In breast cancer, hnRNPM contributes to metastasis by activating alternative splicing changes that promote epithelial–mesenchymal transition (EMT)." (PMID 32023846, 2020). "Elimination of hnRNPM prevents TGFβ induced breast cancer metastasis in mice by decreasing the mesenchymal-related standard CD44 isoform." (PMID 31666932, 2019). "The RNA-binding protein hnRNPM was found to promote breast cancer metastasis by activating the switch of alternative splicing during EMT." (PMID 31737791, 2019). "hnRNPM is associated with increased standard form of CD44 (or CD44 standard, CD44s) in aggressive breast cancer patient specimens." (PMID 31737791, 2019). "Several hnRNPs are reported to overexpress in breast cancer, including hnRNPA1, hnRNPA2, hnRNPI, hnRNPM, and hnRNPK." (PMID 31065692, 2019). "Clinical research also shown that up-regulation of HNRNPM/CEAR protein is associated with the aggressive types of colon and breast cancers." (PMID 27583792, 2016). "The hnRNPM depletion was also accompanied by a general inhibition of TGFβ-induced EMT in HMLE cells which resulted in the reduction of spontaneous lung metastasis numbers in mice with into the mammary fat pad implanted murine T4 breast cancer cells." (PMID 38106992, 2023). "Binding to the GC-rich structural domain of CD44, HnRNPM promotes the skipping of exon 8, which ultimately promotes breast cancer metastasis by enhancing TGFβ signaling and thus activating the switch of alternative splicing that occurs during epithelial-mesenchymal transition (EMT)." (PMID 36052258, 2022). "Notably, the S-633 site on hnRNPM has been found in breast cancer and ischemic tumor tissues by mass spectrometry, suggesting that this site is phosphorylated under certain conditions in vivo." (PMID 35732702, 2022). "In breast cancer cells, loss of HNRNPM inhibits epithelial-mesenchymal transition (EMT), but not cell growth." (PMID 34075878, 2021). "HnRNPM and CD44s expression are positively correlated in breast cancer tissues." (PMID 31737791, 2019). "HNRNPM was found to be upregulated in breast cancer, and it could promote breast cancer invasion and metastasis via regulating CD44 alternative splicing." (PMID 31355266, 2019).
breast carcinoma (continued). "Importantly, HNRNPM regulates the alternative splicing of carcinoembryonic antigen-related cell adhesion molecule-1 (CEACAM1) in breast cancer cells." (PMID 23537109, 2013). "In breast cancer, FMRP catalyzes N6-methyladenosine (m6A) modification of Solute Carrier Family 7 Member 11 (SLC7A11) mRNA and interacts with Heterogeneous Nuclear Ribonucleoprotein M (hnRNPM) to mediate SLC7A11-S splicing, promoting ferroptosis resistance." (PMID 40563420, 2025). "It has been shown that AKAP8 can inhibit the activity of the splicing factor and EMT-promoter heterogeneous nuclear ribonucleoprotein M (hnRNPM), thus inhibiting EMT and breast cancer metastasis in murine models." (PMID 39682684, 2024). "In their subsequent study, the authors showed that coregulation of alternative splicing by hnRNPM and ESRP1 is widespread and primarily antagonistic in breast cancer cells, although a subset of events is regulated concordantly." (PMID 38106992, 2023). "Among all the RBPs (HNRNPU, HNRNPK, RBM5, HNRNPLL, HNRNPH1, HNRNPM, HNRNPA2B1) screened, only SRSF7 (also known as 9G8) was substantially upregulated in hypoxia-treated breast cancer cells." (PMID 34362878, 2021). "The heterogeneous nuclear ribonucleoprotein M (hnRNPM) promotes epithelial-mesenchymal transition (EMT) and metastasis in breast cancer by promoting the biased expression of CD44 standard isoform (CD44s)." (PMID 34362878, 2021). "This review will discuss some recent progresses about the alternative splicing regulators such as CD44, heterogeneous nuclear ribonucleoprotein M (hnRNPM), SND1 and MTDH etc. in breast cancer metastasis." (PMID 31737791, 2019). "Moreover, it has been demonstrated that hnRNPM precisely controls CD44 splice isoform switching during EMT and acts in a mesenchymal-specific manner in breast cancer cells." (PMID 38106992, 2023). "Elucidating the links between hnRNPM and MASTL may give a greater understanding to the role MASTL plays in regulating EMT in breast cancer." (PMID 35732702, 2022). "In addition, evidence from experiments shows the interaction between ESRP1 and hnRNPM is related to EMT and breast cancer subtyping." (PMID 33976726, 2021). "hnRNPM mRNA levels were shown to correlate with aggressive breast cancer subtypes (basal and ER negative) and increased CD44 standard levels in breast cancer patients." (PMID 31666932, 2019). "In addition, hnRNPM binds to the GC-rich domain of CD44 to promote the skipping of exon 8, thus to stimulate breast cancer metastasis." (PMID 31065692, 2019). "hnRNPM, an RNA splicing factor which binds GU-rich RNA cis-elements has been shown to promote EMT and metastasis by regulating alternative splicing in breast cancer." (PMID 27791206, 2016).
gastric cancer (14 papers, 2016 to 2025). A primary or metastatic malignant neoplasm involving the stomach. "It has been found that interaction between circURI1 and heterogenous nuclear ribonucleoprotein M (hnRNPM) caused alternative splicing genes to be regulated, leading to the inhibition of gastric cancer metastasis." (PMID 37489458, 2023). "circURI1 directly interacts with heterogeneous nuclear ribonucleoprotein M (hnRNPM) to modulate alternative splicing of genes, involved in the process of cell migration, thus suppressing gastric cancer metastasis." (PMID 40708910, 2025). "In gastric cancer, circURI1 inhibits metastasis by interacting with HNRNPM to modulate alternative splicing of target genes." (PMID 39567496, 2024). "Together, IQGAP1 and the heterogeneous nuclear ribonucleoprotein M (hnRNPM) have been shown to stimulate gastric cancer cell growth, while their genetic depletion prompts cell cycle arrest that subsequently causes tumor progression." (PMID 36276098, 2022). "For example, circURI1 modulates RNA splicing by sequestering hnRNPM in gastric cancer." (PMID 37461053, 2023). "The circURI1 could interact with heterogeneous nuclear ribonucleoprotein M (hnRNPM) to modulate alternative splicing of multiple genes involved in the process of cell migration, thus suppressing metastasis of gastric cancer." (PMID 36685959, 2022). "In gastric cancer, circURI1 binds and sequesters hnRNPM to modulate AS of genes involved in the process of cell migration, thus suppressing GC metastasis, demonstrated by the fact that circURI1 influenced exon inclusion or exclusion in contrast to hnRNPM." (PMID 39550559, 2024). "Furthermore, the aberrantly expressed circURI1 in gastric cancer could directly recruit hnRNPM to regulate alternative splicing of genes, participating in the malignant proliferation and metastasis of gastric cancer cells." (PMID 38771413, 2024). "CircURI1 behaves as a decoy of heterogeneous nuclear ribonucleoprotein M (hnRNPM) to modulate alternative splicing of VEGFA, thereby inhibiting gastric cancer metastasis." (PMID 35668527, 2022). "Another circRNA, circURI1 also functions as a protein sponge of HNRNPM to modulate alternative splicing of genes such as VEGF1 to inhibit gastric cancer metastasis, and circURI1 is again not conserved in mice." (PMID 37953462, 2024).
Ewing sarcoma (8 papers, 2020 to 2025). A small round cell tumor that lacks morphologic, immunohistochemical, and electron microscopic evidence of neuroectodermal differentiation. "In Ewing sarcomas, hnRNPM-dependent AS promoted drug resistance and drove resistance to the inhibition of the PI3K/AKT/mTOR pathway." (PMID 34294833, 2021). "Similar results were also obtained in SK-N-MC and LAP-35 Ewing sarcoma cells, even though HNRNPM and SRSF3 knockdown in LAP-35 weakly affected DHX9 alternative splicing." (PMID 32023846, 2020). "Our study documents that SRSF3 and hnRNPM downregulation reduces Ewing sarcoma cell proliferation and increases Ewing sarcoma sensitivity to doxorubicin treatment." (PMID 32023846, 2020). "We also found that the expression of hnRNPM and SRSF3, which showed the strongest repression of exon 6A inclusion, is highly associated with the expression of DHX9 in Ewing sarcoma patients." (PMID 32023846, 2020). "Depletion of hnRNPM, and even more of SRSF3, caused a significant reduction in the colony formation potential of Ewing Sarcoma cells." (PMID 32023846, 2020). "On this basis, we indicated hnRNPM as a new potential therapeutic target to counteract Ewing sarcoma malignancy." (PMID 32023846, 2020). "Moreover, hnRNPM guides an AS program involving multiple pre-mRNAs to confer resistance of Ewing sarcoma cells to inhibition of the PI3K/AKT/mTOR signal pathway." (PMID 34145290, 2021). "Importantly, downregulation of SRSF3 or hnRNPM sensitized Ewing sarcoma cells to doxorubicin, a genotoxic agent used in Ewing sarcoma chemotherapy." (PMID 32023846, 2020). "Since high DHX9 expression correlates with poor prognosis, these results suggest that regulation of DHX9 expression by SRSF3 and hnRNPM could represent a prognostic factor in Ewing sarcoma pathogenesis." (PMID 32023846, 2020). "Thus, our results suggest that hnRNPM contributes to Ewing sarcoma malignancy by promoting the high expression of a key regulator of the EWS-FLI1 oncogene." (PMID 32023846, 2020). "Notably, the effect of SRSF3 knockdown on DHX9 protein expression and Ewing sarcoma cell viability was stronger than that elicited by hnRNPM, although displaying a milder effect on the inclusion of the alternative poison exon." (PMID 32023846, 2020). "Thus, we suggest that modulation of SRSF3 and hnRNPM expression and their splicing signature could represent a novel therapeutic opportunity for combined and less aggressive therapy in Ewing sarcoma." (PMID 32023846, 2020). "Therefore, our study suggests that inhibition of hnRNPM or SRSF3 expression could be exploited as a therapeutic tool in Ewing sarcoma." (PMID 32023846, 2020). "Notably, DHX9 expression correlates with that of SRSF3 and hnRNPM in Ewing sarcoma patients." (PMID 32023846, 2020). "Downregulation of SRSF3 or hnRNPM can inhibit the expression of DHX9 and the proliferation of Ewing’s sarcoma cells, and enhance the sensitivity of Ewing’s sarcoma cells to chemotherapy." (PMID 36338707, 2022). "SRSF3 and hnRNPM regulate poison-exon inclusion in DHX9 and sensitize Ewing sarcoma cells to chemotherapy." (PMID 32023846, 2020). "In this study, by employing multiple approaches, we have now identified several splicing factors (SRSF1, SRSF3, and SRSF10, hnRNPK, hnRNPM, and FUS) as regulators of DHX9 splicing in Ewing sarcoma cells." (PMID 32023846, 2020). "Remarkably, silencing of SRSF3 and HNRNPM, impacts on DHX9 expression as well as on Ewing sarcoma cell viability and proliferation, while it reduces survival of Ewing sarcoma cells to doxorubicin treatment." (PMID 32023846, 2020). "In Ewing sarcoma, we previously documented that the inhibition of the mTOR/AKT/PI3K pathway sets in motion an hnRNPM-dependent alternative splicing program that limits the therapeutic efficacy of these pharmacologic inhibitors." (PMID 32023846, 2020). "We identified hnRNPM and SRSF3 as key factors required to suppress exon 6A inclusion and maintain high DHX9 expression in Ewing sarcoma cells." (PMID 32023846, 2020).
Ewing sarcoma (continued). "Collectively these results unveil a novel role for SRSF3 and hnRNPM in the regulation of DHX9 alternative splicing, which also impacts on Ewing sarcoma cell sensitivity to chemotherapeutic treatments." (PMID 32023846, 2020). "Furthermore, downregulation of SRSF3 or hnRNPM inhibited DHX9 expression and Ewing sarcoma cell proliferation, while sensitizing cells to chemotherapeutic treatment." (PMID 32023846, 2020). "Noteworthy, although we focused on the DHX9 poison-exon as a splicing target of SRSF3 and hnRNPM with direct relevance for Ewing sarcoma, our findings do not rule out possible effects of these RBPs on other splicing variants of the same or other genes in this disease." (PMID 32023846, 2020). "Hence, our study suggests that inhibition of hnRNPM and SRSF3 expression or activity could be exploited as a therapeutic tool to enhance the efficacy of chemotherapy in Ewing sarcoma." (PMID 32023846, 2020). "Moreover, our work indicates that the silencing of hnRNPM and SRSF3, the strongest repressors of exon 6A, significantly reduces DHX9 expression and Ewing sarcoma cell survival, thus suggesting the functional relevance of their effects on DHX9 splicing regulation." (PMID 32023846, 2020).
lung carcinoma (6 papers, 2016 to 2025). "For instance, loss of HNRNPM has been shown to induce splicing perturbations and contribute to lung cancer pathogenesis, whereas in CRC, its function is largely determined by the SUMOylation status of lysine 17 (K17), with the SUMOylated form impeding cancer cell glycolysis and tumorigenesis." (PMID 40784984, 2025). "Since hnRNPM is a splicing regulatory factor with a majority of studies focused on its RNA-binding properties and effects on splicing outcomes, we examined hnRNPM-dependent splicing activity in lung cancer." (PMID 39034402, 2024). "The HNRNPA2B1 levels were positively associated with TARDBP (R = 0.83), DHX9 (R = 0.73), HNRNPR (R = 0.77), SRSF1 (R = 0.79), HNRNPD (R = 0.75), and HNRNPM (R = 0.78) genes in lung cancer (all P < 0.001)." (PMID 35529270, 2022). "Taken together, these findings provide insights into how the loss of PARP4 function in LUAD could regulate splicing events, possibly through hnRNPM, thereby contributing to lung cancer pathogenesis." (PMID 39034402, 2024). "However, we and others observe a contrasting tumor-suppressive role for hnRNPM in our respective experimental contexts of lung cancer and prostate cancer." (PMID 39034402, 2024). "To identify PARP4-hnRNPM interaction site(s), we chose the HEK293T cell line which expresses hnRNPM but has low expression of PARP4 compared to the A549 and iSAEC-K lung cancer cells." (PMID 39034402, 2024). "This provided the first indication that hnRNPM and PARP4 likely promoted intron removal from certain genes in lung cancer, but the precise mechanism remains to be determined." (PMID 39034402, 2024). "However, the role of hnRNPM in the context of lung cancer and its regulation by PARP4 has not been clarified." (PMID 39034402, 2024). "Similarly, we identified several splicing proteins, such as SNRPD2, SNRPG, SNRPD3, HNRNPM, HNRNPH3, and SRSF10, in human breast and lung cancer TuNEPs but not in NETs." (PMID 40751052, 2025).